IL2 (interleukin 2)
Diseases named in the same sentence as IL2 in open-access papers (continued):
Sharing a sentence is not in itself a finding about the gene and the disease.
tumor (continued). "In this study we demonstrate that, in addition to its potential role as a tumour suppressor, miR-26a also functions as a modulator of IL-2 expression." (PMID 20441582, 2010). "In MDV-transformed tumour cells, MDV-encoded oncoprotein Meq is thought to play a direct role in the upregulation of IL-2 expression by binding to the IL-2 promoter." (PMID 20441582, 2010). "In fact, in murine models of HNSCC DCs, pulsed with apoptotic tumour cells and activated with interleukin-2, induced strong antigen-specific anti-tumour immunity." (PMID 19473517, 2009). "This study investigated the maintenance of the cytolytic activity of NK cells against K562 cells and autologous tumor after 6 plus 3 infusions of TKD/IL-2-activated effector cells." (PMID 19549307, 2009). "Due to the fact that in vitro TKD/IL-2 stimulation only marginally increased the cytolytic anti-tumor activity in PBMNC obtained from the leukapheresis L4 onwards, the cell-based immunotherapy was interrupted for 3 months after the sixth re-infusion cycle." (PMID 19549307, 2009). "TKD/IL-2-activated cells specifically kill allogeneic, Hsp70 membrane-positive tumor cell lines in vitro." (PMID 19549307, 2009). "Macrophages, dendritic cells, NK cells and Tc cells that are able to recognize, bind and subsequently kill tumor cells, were activated by cytokines such as IL-2 and IFN-γ." (PMID 19292900, 2009). "Other approaches for introducing IL2 into the tumor environment include injection of the cytokine intratumorally and administering intratumoral injections of adenovirus encoding IL2." (PMID 19640287, 2009). "In our previous studies, we have shown that adoptively transferred antigen-specific CD8+ CTL clones are detectable post-infusion, persist in the presence of IL-2 supplementation, are able to traffic to tumor sites, and effect anti-tumor responses." (PMID 19270751, 2009). "According to Argarwal and colleagues, early stage of oral SCC expressed mainly INF-γ and IL-2 genes (Th1 responses), whereas the advanced stage tumours presented IL-4 and IL-10 expression (Th2 response)." (PMID 20049171, 2009). "Results using CD8+ (CTL) clones targeting MART-1 and gp100 in conjunction with low doses of IL-2 demonstrated that infused clones can be detected in appreciable numbers, traffic to tumor sites, and result in tumor regression." (PMID 19270751, 2009). "Intravenous, subcutaneous or intra-pleural administration of IL-2 has shown some effects on tumour regression in MPM, supporting the use of IL-2 in clinical trial settings." (PMID 19935800, 2009). "In conclusion, this study indicates that treatment of MPM with intra-pleural IL-2 leads, on one hand to an increase in tryptase-positive MCs, and in CD8+ and Foxp3+ lymphocytes, and on the other hand to an inhibition in tumour-associated vascularity." (PMID 19935800, 2009). "Herein, we report the kinetics of the anti-tumor immune responses in this patient who received a total of 9 re-infusions of ex vivo TKD/IL-2-activated, autologous leukapheresis products over a 12-month period and the clinical follow-up for 1 year." (PMID 19549307, 2009). "Murine models demonstrated that IL-15 enhances in vivo anti-tumor activity of adoptively transferred T cells, which is further enhanced in combination with an anti-IL-2 antibody." (PMID 19175928, 2009). "Membrane-bound heat shock protein 70 (Hsp70) serves as a tumor-specific recognition structure for Hsp70-peptide (TKD) plus IL-2 activated NK cells." (PMID 19549307, 2009). "Astragalus appears to have anti-tumour activity where its potentiates LAK cell activity in vitro when used in combination with IL-2." (PMID 19674474, 2009). "After confirmation of transduction by flow cytometry for hCD40L (94%) and IL-2 secretion (2,412 pg/ml/106 leukemic cells), the gene-modified tumor vaccine was irradiated (30 Gy) and cryopreserved." (PMID 19922650, 2009).
tumor (continued). "A number of studies have been reported demonstrating the ability of interferon alpha and interleukin-2 (IL-2) to engender a tumour response." (PMID 18362942, 2008). "The treatment of the epigastric area with 9.8 × 109 DC+AK and 4.5 × 105U IL2 reduced the tumor cell count from 6.6 × 108 to 6 × 105 (1/1100)." (PMID 19055844, 2008). "The incidence of vascular invasion has been shown to be higher in tumours removed in the follicular phase, as have levels of insulin like growth factor, interleukin-2, natural killer (NK) activity and various gene changes." (PMID 18087287, 2008). "This study also demonstrated that DAB/IL2-mediated depletion of Tregs followed by vaccination with RNA-transfected DCs increased the activation of tumor-specific T cell responses compared to vaccination alone." (PMID 18334033, 2008). "After the drainage of ascites, we intraperitoneally infused activated killer cells and dendritic cells from the patient's tumor-draining lymph nodes, together with 4.5 × 105U interleukin-2 in 50 ml saline by 2.1 ml/hour infuser balloon." (PMID 19055844, 2008). "It has been shown that the addition of systemic Interleukin-2 (IL-2) therapy to tumor immunization plays a pivotal role in increasing the frequency of immune cancer rejections." (PMID 18384692, 2008). "Probably directed in part by PGE2, based on reduced production of anti-tumor Th1 cytokines (TNFα, IFNγ and IL-2) and increased production of Th2 cytokines (IL-4, IL-10 and IL-6)." (PMID 19455240, 2007). "Only one of six mice (17%) in each group treated with the Neuro-IL2/IL12 vaccine or the AJ-IL2/IL12 vaccine developed a tumour and the other five in each group (83%) remained tumour free for over 40 days, a significant improvement over controls (P<0.01)." (PMID 17595664, 2007). "Anti-CD45 staining demonstrated that tumours vaccinated intratumorally with AJ-IL2/IL12 or Neuro-IL2/IL12 had extensive infiltration of leukocytes, particularly around the tumour periphery." (PMID 17595664, 2007). "Complete tumour growth inhibition was seen in seven of 10 (70%) mice treated with the Neuro-IL2/IL12 vaccine and nine of 10 (90%) mice treated with the AJ-IL2/IL12 vaccine." (PMID 17595664, 2007). "Intratumoral treatment with the Neuro-IL2/IL12 vaccine resulted in significant tumour growth retardation compared to control mice receiving RPMI." (PMID 17595664, 2007). "Lungs from tumor-bearing control animals treated with IL-2 alone contained relatively few infiltrating cells." (PMID 18001476, 2007). "Our study attempts to reveal the maximal potential of IL-2 activated human NK cells in eliminating tumor cells." (PMID 17389917, 2007). "T cells rescued by IL-2, IL-15 and IL-21 killed peptide coated target cells and tumor cells more efficiently than T cells cultured with IL-7 or without cytokine supplementation." (PMID 17406677, 2007). "As well as mediating adaptive immune functions, IL-12 has angiostatic effects, and histological evaluation of tumours from mice treated with Neuro-IL2/IL12 or AJ-IL2/IL12 vaccines suggested that the vascularisation was reduced compared to control tumours." (PMID 17595664, 2007). "The median tumour-specific survival time was 18 (±4) months in the IL-2 group and 10 (±1) months in the control group (P=0.015)." (PMID 17031403, 2006). "Having shown that treatment with IL-21+ low-dose IL-2 significantly delayed early tumor growth, we compared the effects of the three different cytokine regimens on long-term tumor regression and overall survival beyond 30 days." (PMID 16772043, 2006). "There have, to our knowledge, been no reports describing the potential synergy of IL-21 + low-dose IL-2 in this or other tumor models." (PMID 16772043, 2006). "Tumour-specific survival in the IL-2 group and the control group was 98 vs 81% after 1 year and 86 vs 73% after 5 years (P=0.04)." (PMID 17031403, 2006).
tumor (continued). "Seven days later therapy was initiated with 5 daily IP injections (days 14–18 post tumor inoculation) of IL-2 alone, IL-21 alone or both cytokines." (PMID 16772043, 2006). "By day 42 previously regressing tumors in a subset of IL-21 + IL-2 treated mice began to grow again, reaching a mean tumor size of 25–50 mm2." (PMID 16772043, 2006). "IL-21 alone and IL-2 alone both delayed tumor progression, but only IL-21 significantly augmented long-term survival (20%) compared to the control group." (PMID 16772043, 2006). "In both models, IL-2 and IL-15 delayed tumor growth, but only IL-21 resulted in significant prevention of tumor progression and improved survival beyond 50 days from tumor challenge." (PMID 16772043, 2006). "It has been shown that when patients with resectable recurrent CRC are treated with interleukin-2 before surgery, there is an increase of eosinophilic infiltration in tumour tissue, indicating that interleukin-2 increases the host response to the tumour." (PMID 17026740, 2006). "The cumulative long-term survival of mice from all groups from three experiments followed out to 150 days post tumor inoculation showed that IL-21 + IL-2 treated mice had significantly better survival (46%) compared to all other groups." (PMID 16772043, 2006). "On this background, we conducted a prospective controlled phase II trial to assess the effect of immunomodulation with interleukin-2 (IL-2) in the potentially critical perioperative period in patients with RCC undergoing tumour nephrectomy." (PMID 17031403, 2006). "By day 21, vaccination combined with IL-21 + IL-2 treatment inhibited tumor growth significantly better than vaccination alone (p = 0.0013) and vaccination combined with IL-2 (p = 0.0044) or with IL-21 (p = 0.044)." (PMID 16772043, 2006). "of tumour-specific survival were 98% (±2%) and 86% (±7%) in the IL-2 group and 81% (±5%) and 73% (±6%) in the control group, respectively (P=0.043)." (PMID 17031403, 2006). "At peak expansion (21 days post vaccination), the combination of IL-21 plus IL-2 resulted in a 2- to 3-fold higher absolute number of circulating tumor antigen-specific pmel CD8+ T cells than was stimulated by IL-2 or IL-21 alone." (PMID 16772043, 2006). "By day 28, vaccination combined with IL-21+ IL-2 again inhibited tumor growth significantly better than vaccination alone (p < 0.0001) and vaccination combined with IL-2 (p = 0.0006) or with IL-21 (p = 0.0033)." (PMID 16772043, 2006). "All surviving mice in the IL-21 + IL-2 test group were tumor-free at day 150-post tumor inoculation." (PMID 16772043, 2006). "Approximately half of the mice treated with low dose IL-2 demonstrated a modest delay of tumor growth to ≥ 200 mm2 until approximately day 42, and there was one long-term survivor." (PMID 16772043, 2006). "Cultures received IL-2 from day 3 on and were restimulated with irradiated autologous tumor cells and IL-2 every week." (PMID 16281981, 2005). "Since Dlg is a tumor suppressor gene product in Drosophila, it is an attractive candidate to play a role in IL-2-independent growth induction in CTLL-2 cells." (PMID 16042787, 2005). "Each cycle of stimulation results in rapid death of the tumour targets, followed by IL-2-driven proliferation of CAR-grafted T cells." (PMID 15266309, 2004). "In this regard, adenoviral-mediated expression of both the IL-2 and IL-12 cytokine genes in several solid tumor models has been found to induce strong and specific anti-tumor responses." (PMID 15485577, 2004). "Most of the clinical experience with IL-2 as an adjuvant to vaccine was gained with high-dose schedules or when tumour cells were transduced to secrete IL-2." (PMID 14970852, 2004). "So far, three different phase I trials have been performed in NB patients unresponsive to conventional treatments, by employing either autologous or allogeneic NB tumour cells engineered to produce IL-2, alone or in combination with lymphotactin." (PMID 15150552, 2004).
tumor (continued). "In summary, the present study has assessed the Ki-67 (MIB-1) tumour proliferation marker in mRCC at baseline and during IL-2- and IFN-α based immunotherapy." (PMID 14760375, 2004). "No significant cytotoxic activity was seen when DC were pulsed with tumor lysate of Dan-G cells were used with IL-2 transfected CIK cells." (PMID 15329148, 2004). "Patient 4 is treated with IL-2 for the longest period, 15 months now and still demonstrates slow tumour regression." (PMID 14970852, 2004). "It appears, therefore, that the autologous vaccine exerted a priming effect, possibly generating tumour-specific immune effector cells, which were activated upon the addition of IL-2." (PMID 14970852, 2004). "In contrast, 10 of 24 patients showed complete or partial regression of their tumours, following the phase of IL-2 administration." (PMID 14970852, 2004). "In a xenogeneic model, we have previously shown that IL-2-transfected human NB cells inhibited the growth of parental tumour cells coinjected in nude mice." (PMID 15150552, 2004). "PROTEIN-BOUND POLYSACCHARIDE K restores host immune functions that are suppressed by tumour or antitumour chemotherapeutic agents, thereby producing IL-2 and IFN γ, and stimulating the activities of LAK and NK cells." (PMID 14997197, 2004). "In the present study, we have evaluated the relationship between the amount of cytokine production by the combination IL-2 and IL-12 and the in vitro effective anti-tumor activity." (PMID 15485577, 2004). "In this report, we investigated the ability of peripheral (PBL) and tumor- infiltrating (TIL) lymphocytes of undifferentiated NPC patients to produce in vitro three interleukins (IL-2, IL-6, IL-10) and three immunoglobulin isotypes (IgM, IgG, IgA)." (PMID 15450122, 2004). "This set of experiments demonstrates that the C595scFv-Fc-IL2 fusion protein bound to MUC1-positive tumour cells activates resting NK cells to tumour cell lysis." (PMID 12966437, 2003). "We report the somewhat unexpected finding that intratumoral injection of adenovirus expressing B7-1/IL-2 induces complete tumour regression in 76% of oestradiol-supplemented mice, while only 18% of the tumours regressed in the oestrogen-depleted group." (PMID 12865933, 2003). "We examined the immunological effect of irradiated N2A cells expressing IL-2, IL-12, or a combination of the two cytokines on parental tumours." (PMID 12771934, 2003). "In vivo the cytokine levels required for complete tumour growth inhibition by parental N2A cells were 235 ng/24 h IL-12 and 40 ng/24 h IL-2." (PMID 12771934, 2003). "MUC1-positive MCF7 tumour cells were incubated with C595scFv-Fc-IL2 fusion protein and IL2, respectively, and cocultured with resting NK cells." (PMID 12966437, 2003). "Taken together, the fusion proteins C595scFv-Fc and C595scFv-Fc-IL2 specifically bind to MUC1-positive tumour cells via the anti-MUC1 scFv domain, the C595scFv-Fc-IL2 protein binds in addition via IL2 to CD25+, activated lymphocytes in vitro." (PMID 12966437, 2003). "Such recognition led to lysis of HER-2/neu+ tumour targets and also to secretion of IL-2 and IFN-γ by the MD.45-HER effector CTL." (PMID 12698199, 2003). "Mice that had undergone complete regression of the PyMT tumours after treatment with AdB7-1/IL-2 were rechallenged with a second inoculation of 1 × 109 PyMT cells 90 days after initial vector administration, on the left hind flank." (PMID 12865933, 2003). "These properties make the C595scFv-Fc-IL2 fusion protein a suitable candidate for the immunotherapy of MUC1-positive tumours." (PMID 12966437, 2003). "In a few cases (three) with high cumulative IL-2 doses and severe inflammatory reaction, the necrosis exceeded the tumour tissue and resulted in a sterile ulceration of the skin, which healed within weeks of therapy completion." (PMID 14583759, 2003).
tumor (continued). "Recognition of HER-2/neu+ primary tumour cells isolated from patients' ascites led to 15- to 30-fold increased secretion of IL-2 levels as compared to background levels." (PMID 12698199, 2003). "From the in vitro data presented here, the addition of IL-2 resulted in at least a four-fold decrease in the cell number required to effect a total repression of tumour cell line growth." (PMID 12671714, 2003). "Such alterations, however, can be reverted by removal of TIL from the tumour site and coincubation with IL-2." (PMID 12610520, 2003). "Administration of IL-2 has been shown to promote antitumour immunity, presumably by alleviating the anergic block seen in T cells in some tumour models and thereby preventing the onset of anergy." (PMID 12865933, 2003). "Administration of 1 × 109 PFU of the B7-1/IL-2 vector resulted in complete tumour regression within 3 weeks in 76% of OVX+E2-treated animals, while only 18% of the placebo animals were cured." (PMID 12865933, 2003). "When given systemically, the concentration of IL-2 within the tumour is several magnitudes lower than under intralesional therapy." (PMID 14583759, 2003). "Endo-GrB was located both in cytoplasm and nuclei of the RB-reconstituted tumour cells; a comparable pattern was observed for IL-2-activated PBL GrB (Lym-GrB)." (PMID 12838314, 2003). "Vaccination of established tumours with IL-12-producing cells exhibited a clear effect with reduced tumour growth in the presence of IL-2." (PMID 12771934, 2003). "The anti-MUC1 scFv-Fc-IL2 fusion protein harbours the C595 scFv domain for targeting IL2 to MUC1-positive tumours." (PMID 12966437, 2003). "Further studies on the mechanism of tumour regression induced by local treatment with IL-2 are needed." (PMID 14583759, 2003). "Results presented here suggest the C595scFv-Fc-IL2 fusion protein as suitable immunocytokine for the specific immune modulation in the vicinity of MUC1-positive tumours." (PMID 12966437, 2003). "Taken together, it is strongly suggested that OK-432 plus IL-2 stimulation induces autologous tumour-reactive CD4+ Th1 killer lymphocytes." (PMID 14612896, 2003). "Resting NK cells, in contrast, are activated by the C595scFv-Fc-IL2 fusion protein to tumour cell lysis." (PMID 12966437, 2003). "Mice receiving cells transfected with IL-12 or a combination of IL-2 and IL-12 remained tumour free for at least 75 days." (PMID 12771934, 2003). "Many of its functions are mediated through the actions of IFN-γ, but it has also been shown to synergise with IL-2 to generate lymphokine-activated killer (LAK) cells against tumour targets." (PMID 12771934, 2003). "In conclusion, these data provide novel in vivo evidence of the possible contribution of lymphocyte subsets in the tumour reduction in responding patients during interleukin-2 based immunotherapy." (PMID 12107842, 2002). "Since hypoxia is a critical factor in the response of tumours to radiation treatment, we compared the radiation response of IL-2-transfected tumours to that of parental EMT6 tumours." (PMID 10732769, 2000). "One group of rats was treated with histamine alone (4 mg kg–1s.c. as daily injections from day 6 after intracranial tumour implantation), another group with IL-2 alone as a continuous subcutaneous infusion and a third group with both histamine and IL-2." (PMID 10952789, 2000). "Biotherapy including interleukin-2 (IL-2) treatment seems to be more effective outside the central nervous system when compared to the effects obtained when the same tumour is located intracerebrally." (PMID 10952789, 2000). "The in vivo radiation response results demonstrated that IL-2-transfected tumours were more sensitive to radiation than parental EMT6 tumours." (PMID 10732769, 2000). "The data indicate that in human carcinomas, endogenous IL-2 promotes growth and protects tumour cells from apoptosis." (PMID 10555752, 1999).